SLC2A4RG (SLC2A4 regulator)
Description:
Transcription factor involved in SLC2A4 and HD gene transactivation. Binds to the consensus sequence 5'-GCCGGCG-3'.
Synonyms: GEF; HDBP-1; HDBP1; GLUT4EF; Si-1-2; Si-1-2-19
Tractability: No criterion of Open Targets' tractability assessment is met for any kind of drug.
Gene: Protein-coding gene on chromosome 20 (63,739,759 to 63,744,050, forward strand). Ensembl gene ENSG00000125520.
Subcellular location: Cytoplasm; Nucleus
Subcellular location (Human Protein Atlas): Nuclear speckles
Gene Ontology:
Molecular function: DNA-binding transcription factor activity; RNA polymerase II cis-regulatory region sequence-specific DNA binding
Biological process: regulation of DNA-templated transcription; regulation of transcription by RNA polymerase II
Cellular component: nucleus; cytoplasm
Genetic constraint (gnomAD): Loss-of-function variants: 22 observed, 32.08 expected, observed/expected ratio (o/e) 0.69, 90% interval 0.49 to 0.98. The synonymous counts are far from expectation, so gnomAD's model fits this gene poorly and the ratio says little. Missense variants: 531 observed, 476.64 expected, observed/expected ratio (o/e) 1.11, 90% interval 1.04 to 1.2. Synonymous variants: 302 observed, 219.94 expected, observed/expected ratio (o/e) 1.37, 90% interval 1.25 to 1.51.
Homologues: Orthologues: chimpanzee SLC2A4RG (99% identical), macaque SLC2A4RG (88% identical), guinea pig SLC2A4RG (71% identical), pig SLC2A4RG (59% identical), dog SLC2A4RG (50% identical), tropical clawed frog slc2a4rg (38% identical), Drosophila melanogaster Glut4EF (28% identical). Paralogues in human: ZNF704 (40% identical), ZNF395 (34% identical).
Diseases named in the same sentence as SLC2A4RG in open-access papers:
SLC2A4RG is named in the same sentence as 15 diseases in open-access papers, as found by Europe PMC text mining. Sharing a sentence is not in itself a finding about the gene and the disease. The quoted sentences say what the papers report.
breast carcinoma (2 papers, 2024 to 2025). "Given that bone is a common site for breast cancer metastasis, particularly at advanced stages, SLC2A4RG may play a role in bone integrity and, by extension, BMD." (PMID 39431290, 2025).
glioma (2 papers, 2016 to 2021). A benign or malignant brain and spinal cord tumor that arises from glial cells (astrocytes, oligodendrocytes, ependymal cells). "In this study, a three-gene signature (MN1, HOXA7, and SLC2A4RG) could divide lower grade glioma patients into low-and high-risk groups, with longer OS obtained in the former group." (PMID 27677590, 2016). "Three genes (HOXA7, SLC2A4RG and MN1) were selected to establish a three-gene signature in lower grade gliomas." (PMID 27677590, 2016).
Huntington disease (2 papers, 2014 to 2020). Huntington disease (HD) is a rare neurodegenerative disorder of the central nervous system characterized by unwanted choreatic movements, behavioral and psychiatric disturbances and dementia. "In a study of Huntington disease, SLC2A4RG was found to cooperate with a key cis-element and shuttle to and from the nucleus." (PMID 32719717, 2020).
inflammatory bowel disease (1 paper, 2018). A spectrum of small and large bowel inflammatory diseases of unknown etiology. "Genetic variants at SLC2A4RG have been found to be associated with inflammatory bowel disease and prostate cancer." (PMID 29456763, 2018).
cancer (3 papers, 2021 to 2024). A tumor composed of atypical neoplastic, often pleomorphic cells that invade other tissues. "Indeed, downregulation of several glycolysis genes deeply involved in cancer progression (ENO1, ME1, SLC2A4RG, PFKL and DLAT) was confirmed by RT-qPCR in siRNF40-treated HCC1806 cells." (PMID 37770435, 2023). "The genes preferentially mutated in metastases were MYLK, PEAK1, SLC2A4RG, EVC2, XIRP2, PALB2, and ESR1 (five of which are not significantly mutated in any type of human primary cancer)." (PMID 34771579, 2021).
tumour (3 papers, 2021 to 2023). "Differently from BRAF-like PTCs, RAS-like tumours show higher levels of the inducible transporter SLC2A4 (alias Glut4) and of its main regulator, the transcription factor SLC2A4RG, whose expression levels are positively correlated across tumour samples." (PMID 37198319, 2023). "Lastly, SLC2A4RG, with its involvement in glucose metabolism, is connected to deviations in metabolic activities instrumental in tumor progression." (PMID 37314494, 2023).
intestinal disorder (1 paper, 2016). A non-neoplastic or neoplastic disorder that affects the small or large intestine. "HDBP1 is also known as SLC2A4 regulator (SLC2A4RG) or GLUT4 enhancer factor (GLUT4EF), and have been linked to increased risk of intestinal disorders." (PMID 27527215, 2016).
SLC2A4RG also shares sentences with these, for which no sentence is quoted: lung adenocarcinoma (2 papers); atherosclerosis (1); brain disease (1); colon cancer (1); Crohn disease (1); glioblastoma (1); prostate carcinoma (1); ulcerative colitis (1).